PDCD1LG2 (programmed cell death 1 ligand 2)
Diseases named in the same sentence as PDCD1LG2 in open-access papers (continued):
Sharing a sentence is not in itself a finding about the gene and the disease.
tumor (1,468 papers, 2011 to 2026). "The result showed that the genes (including CD276, CD274, and PDCD1LG2) had functions on T-cell co-inhibition contributing to tumor cell evasion were enriched in high-risk groups and become important targets for blockade-based immunotherapy in cancer;." (PMID 38665430, 2024). "We also found that tumor PDCD1LG2 expression was associated with improved LMSF, which was opposite to the results in sPDL2." (PMID 38730580, 2024). "Both the ‘basal-like’ tumours and ‘activated’ stromal subtypes are associated with poorer survival, further supporting the conclusion that high PDCD1LG2 expression is a prognostic marker of poor clinical outcome in patients with PDAC." (PMID 36138073, 2022). "Among the PDCD1LG2 SNPs, rs2381282 (p < 0.001), rs12237624 (p = 0.019), and rs78096119 (p = 0.019) risk alleles were negatively associated with PD-L2 expression in non-tumor tissues." (PMID 34631591, 2021). "Programmed cell death-ligand 1 (PDL1, encoded by CD274) and 2 (PDL2, encoded by PDCD1LG2) are expressed by antigen presenting cells and some tumours, and bind to programmed cell death protein 1 (PD1, encoded by PDCD1) on effector T cells." (PMID 32582553, 2020). "CD276, PDCD1LG2 (PD-L2) were a member of the B7 transmembrane glycoprotein family, and their expression were associated with poor prognosis and tumor immune escape of NSCLC." (PMID 32699529, 2020). "Our MR-derived protective association suggests PDCD1LG2 may exert tumor-suppressive effects in GC pathogenesis under certain genetic or microenvironmental contexts, challenging conventional oncogenic paradigms and warranting mechanistic exploration." (PMID 40388730, 2025). "In addition, the protein encoded by PD-L2 and PDCD1LG2 is one of the important components of the PD-1/PD-L1 and PD-L2 axis, which is involved in tumor immune escape." (PMID 37273084, 2023). "Apart from TAMs, Treg cells, known as the immunosuppressive class of CD4+T cells suppress anti-cancer immunity, and CAFs, which promote tumor growth, angiogenesis, invasion and metastasis and remodel extracellular matrix, were also positively associated with pdcd1lg2 expression in this study." (PMID 37006239, 2023). "In addition, the association between CD274/PDCD1LG2 and the tumor infiltration level, tumor mutation burden (TMB), microsatellite instability (MSI), mismatch repair (MMR), and DNA methyltransferase (DNMT) were analyzed in the different tumor types." (PMID 33833994, 2021). "Analysis of expression of CD274 (PD-L1) and PDCD1LG2 (PD-L2) is shown with respect to stage - there was a significant increase in PD-L1 (CD274) expression associated with increased tumor stage (pT1-T2+ p=0.0031, pTa-T2+ p=<0.0001; one-way ANOVA with Tukey’s multiple comparison)." (PMID 33718196, 2021). "Furthermore, the expression of CD274 and PDCD1LG2 was correlated with tumor mutation burden (TMB), microsatellite instability (MSI), mismatch repair (MMR), and DNA methyltransferase (DNMT) of different types of cancers." (PMID 33833994, 2021). "Among the 6 immune checkpoints, CTLA4, CD86, and PDCD1LG2 were highly expressed in the high-risk group (Wilcoxon rank-sum test, p < 0.05), suggesting that these genes may serve as key targets for anti-tumor therapy in CRC." (PMID 35719389, 2022). "Conversely, sporadic tumours displayed increased infiltration of protumorigenic M2-like macrophages and increased expression of immune checkpoints PDCD1LG2 and CD40LG." (PMID 41535448, 2026). "Targeting intracellular PD-L1 has been shown to promote antitumor immune responses in some mouse tumor models, and nuclear PD-L1 upregulates several genes involved in immunosuppression, including PDCD1LG2, BIRC3, RELB, and VSIR." (PMID 39996786, 2025). "The association between PIEZO1 and tumor microenvironment scores (Stromal, Immune, ESTIMATE) or immune checkpoint markers (CD274, CTLA4, LAG3, PDCD1, PDCD1LG2) were analyzed using the R language." (PMID 40977743, 2025).
tumor (continued). "PDCD1LG2 (programmed death-ligand 2), a key immune checkpoint regulator, exhibits context-dependent roles in tumor biology." (PMID 40388730, 2025). "Further exploration of tumor‐associated immune checkpoints and the risk model is underway, revealing the high expression of TIGIT, PDCD1, and PDCD1LG2 in the low‐risk group." (PMID 38546286, 2025). "Fourth, PIEZO1 shows positive associations with tumor microenvironment scores (Stromal/Immune/ESTIMATE) and immune checkpoint markers (CD274, CTLA4, LAG3, PDCD1, PDCD1LG2)." (PMID 40977743, 2025). "Several inhibitory markers, including CD276, HAVCR2, CTLA4, PDCD1LG2, LAIR1, and ADORA2A, were significantly upregulated in the high-risk group (p < 0.05), suggesting an immunosuppressive tumor microenvironment." (PMID 40963600, 2025). "MAP2K2-KO in tumor cells also results in significant overexpression of the immune checkpoint receptor ligand PDCD1LG2 (LFC: 0.2, Q: 0.01) and downregulation of the marker of cytotoxicity GNLY (LFC: −0.29, Q: 0.03)." (PMID 40081369, 2025). "Combined with TCGA and CGGA cohort, TRIM56 was most closely correlated with LAIR1, CD44, PDCD1LG2 and CD274, and oncoplots were used to display the tumor mutation gene microlandscape of TRIM56 high expression group and low expression group." (PMID 38348047, 2024). "LGALS3 expression showed a significant positive association with CD274, TIGIT, PDCD1, HAVCR2, CTLA4, LAG3, as well as PDCD1LG2 after adjustment for tumor purity in HCC." (PMID 38643145, 2024). "Of note, we observed heightened expression of PDCD1LG2, which is a negative regulator of T-cells that can be expressed on stromal and/or tumour cells to repress immune recognition." (PMID 39070657, 2024). "scRNA-seq of Kaede-red CD45+ cells in tumour-dLNs (integrated with CD45+ cells from control LNs) included a prominent Ccr7+Cd274+Pdcd1lg2+ DC cluster among myeloid cells." (PMID 38267413, 2024). "The expression of its ligands, programmed death ligand 1 (CD274, PD-L1) and programmed death ligand 2 (PDCD1LG2, PD-L2, CD273), is induced by inflammatory cytokines released after TR activation, on tumor cells." (PMID 37215135, 2023). "A notable correlation was observed between risk score and expression of CTLA4, HAVCR2, PDCD1, PDCD1LG2, and TIGIT, indicating risk scores represent tumor-induced immunosuppression." (PMID 37404760, 2023). "The ligand of programmed death 1 (PD-1) (CD274 and PDCD1LG2) is the key mechanism leading to tumor immune escape." (PMID 37510310, 2023). "Consistently, the corresponding immune checkpoint ligands CD274 (PD‐L1) and PDCD1LG2 (PD‐L2) were barely expressed in both cancer cells and other infiltrating immune/stromal cells in the tumor microenvironment." (PMID 36529697, 2023). "Consistently, the corresponding immune checkpoint ligands CD274 (PD‐L1) and PDCD1LG2 (PD‐L2) were barely expressed in either cancer cells or other infiltrating cells in the tumor microenvironment." (PMID 36529697, 2023). "A notable association was observed across risk score and the expression of CTLA4, HAVCR2, PDCD1, PDCD1LG2, and TIGIT, indicating risk scores represent tumor-induced immunosuppression." (PMID 37404760, 2023). "The classical immune checkpoint molecules such as PD1 and PDCD1LG2 were highly expressed in cluster 1 in the study of tumor immune microenvironment in two clusters of patients." (PMID 36159780, 2022). "Immune checkpoints such as PDCD1LG2, ICOS, CD28, and CD40 were found to be substantially expressed in the high-risk group, indicating that the tumor microenvironment of the high-risk group had a strong immunosuppressive effect." (PMID 36479092, 2022). "We also investigated correlations between CD274 and PDCD1LG2 and immunotherapeutic biomarkers, including mismatch repair (MMR), tumor mutation burden (TMB), microsatellite instability (MSI), and DNA methylation." (PMID 36276934, 2022).
tumor (continued). "Next, considering the potential tumor suppressor role of EPHX3 in HNSCC, we examined the association between EPHX3 and CD274, IL1B, IL1A, PDCD1, and PDCD1LG2." (PMID 35401746, 2022). "Conversely, isolated MES cells intrinsically express CCL2 and PDCD1LG2, which can facilitate a pro-tumor microenvironment by attracting monocytes and inhibiting T-cell proliferation/cytokine production, respectively." (PMID 35810190, 2022). "CD274 (PD-L1) and PDCD1LG2 (PD-L2) are involved in immunosuppression by tumor cells to evade cytotoxic T cell mediated killing and are associated predominantly with the EBV+ sub-type in a STAT1 driven manner as discussed later in this review." (PMID 35844493, 2022). "Taube and colleagues have reported that the areas of tumor cell PDCD1LG2 expression were adjacent to immune infiltrates in the CM case." (PMID 35938036, 2022). "Analysis of PDCD1LG2 expression in these subtypes identified significantly elevated expression in ‘basal-like’ versus ‘classical’ tumours and in PDAC with an ‘activated’ stromal subtype versus those classified as ‘low’." (PMID 36138073, 2022). "More importantly, the expression level of CD274 and PDCD1LG2 was significantly correlated with the degree of Estimation of STromal and Immune cells in MAlignant Tumor tissues using the Expression data (ESTIMATE)." (PMID 33833994, 2021). "The activation and proliferation of T cells with high expression of programmed cell death 1 (PD-1) are decreased; tumor cells with high expression of programmed cell death 1 ligand 1 (PD-L1)/programmed cell death 1 ligand 2 (PD-L2) are more likely to escape." (PMID 34513678, 2021). "In our data, expression of PD-1 (PDCD1) was higher in CD8+ T cells in the tumor than in a normal lung, and PD-L1 (CD274) and PD-L2 (PDCD1LG2) were highly expressed in macrophages both from a normal lung and tumor." (PMID 33918618, 2021). "In our study, we found a significant positive correlation between C10orf54 and genes such as TIM-3, TIGIT, and PDCD1LG2, which are responsible for tumor immune escape and immune suppression in human cancers." (PMID 31781843, 2020). "The only case with amplification of both CD274 and PDCD1LG2 loci had correspondingly high mRNA expression of PD-L1, as well as strong PD-L1 and high PD-L2 protein expression within the tumor fields." (PMID 33424844, 2020). "Different subtypes were notable for particular molecular pathogenetic features; for example, EBV-positive tumours harboured recurrent PIK3CA mutations, along with amplifications involving JAK2, CD274 (encoding PD-L1) and PDCD1LG2 (encoding PD-L2)." (PMID 31790410, 2019). "CD274, also known as PDL1, and PDCD1LG2 takes part in PD-1/PD-L1, PD-L2 pathway, which is involved in anti-tumor immune response." (PMID 29721214, 2018). "TAMs showed a M2-like phenotype characterized by expression of Cd206 (Mrc1), Cd163, Pdl2 (Pdcd1lg2), Chi3i3, Arg1, as well as tumour-promoting molecules involved in invasion and metastasis like MMPs." (PMID 27150562, 2016). "The EBV-positive tumours have been correlated with PIK3CA mutations; high levels of DNA hypermethylation; and amplification of JAK2, PD-L1, and PDCD1LG2." (PMID 27514667, 2016). "In the model of adaptive immune resistance IFNγ-driven expression of PD1 ligands CD274 and PDCD1LG2 on tumour cells and the microenvironment limits local T-cell responses." (PMID 26362649, 2015). "Moreover, increased expression of immune checkpoint molecules, such as PD-L1 (CD274) and PD-L2 (PDCD1LG2), in high-risk patients suggests enhanced tumor immune evasion." (PMID 41153362, 2025). "In addition to LAG3, two other important checkpoint molecules expressed by tumor cells, namely, the PD-L1 ligand (CD274) and its paralog PDCD1LG2, were significantly decreased in the high-risk groups." (PMID 40302936, 2025).
tumor (continued). "TIPC subtypes also showed a strong association with the level of tumor-infiltrating PDCD1 (PD-1)+ cells and tumor PDCD1LG2 (PD-L2) expression, suggesting immune checkpoint-related mechanisms may be involved in sculpting T-cell spatial distributions." (PMID 39965007, 2025). "While it typically promotes tumor progression through immune evasion – evidenced by elevated PDCD1LG2 expression in GC tissues correlating with immunosuppressive microenvironments and chemoresistance – emerging preclinical studies reveal paradoxical immunostimulatory effects." (PMID 40388730, 2025). "Notably, we observed increased expression of PDCD1LG2, which is a negative regulator of T cells that can be expressed on stromal and/or tumour cells to repress immune recognition." (PMID 41013689, 2025). "Additionally, immune checkpoint molecules (e.g., CCR4, CD27, CD274, CD68, CTLA4, PDCD1, and PDCD1LG2) were significantly upregulated in the AERShigh group (all p < 0.01), suggesting potential impairment of the anti-tumor immune response." (PMID 39464883, 2024). "In addition, the relationship between NOLC1 and CD274, PDCD1, and PDCD1LG2, which are important immune checkpoints for tumor immune escape, was also explored." (PMID 37670166, 2023). "Furthermore, T-47D and BT-474 cell lines recovered cell-intrinsic CTLA-4 and PDCD1LG2 (PD-L2) expression after tumor-immune cell interactions, respectively." (PMID 36901916, 2023). "Therefore, our data further support the essential role of intrinsic CD274 (PD-L1) and PDCD1LG2 (PD-L2) in maintaining BC’s tumor stem cell phenotype." (PMID 36901916, 2023). "In addition to PD-L1, programmed cell death 1 ligand 2 (PD-L2) is another corresponding partner of PD-1 and is expressed on tumor cells and antigen presenting cells." (PMID 37174080, 2023). "We assessed tumor immune microenvironment through the CIBERSORT algorithm, which demonstrated the upregulation of M1 Macrophages and activated DCs and high expression of key immune checkpoint molecules (CTLA4, PDCD1LG2, and HAVCR2) in high-risk group." (PMID 37730669, 2023). "Of note, these tumor-specific neutrophils might act as tumor promoters by overexpressing Vegfa, Cd274, Pdcd1lg2, and Lgals3, leading to these cells being further defined as tumor-promoting neutrophils." (PMID 36650153, 2023). "Finally, we have determined that neoplastic cell-intrinsic CTLA-4, PCDC1 (PD1), CD274 (PD-L1), and PDCD1LG2 (PD-L2) expression is dynamic and varies depending on BC immunophenotype and tumor-immune cell interactions." (PMID 36901916, 2023). "Finally, the enrichment analysis suggested that CD274 and PDCD1LG2 were not only involved in pan-cancer immunomodulatory regulation but also contributed to tumor metastasis." (PMID 36276934, 2022). "To further investigate the relationship between KIRP tumor immunity, we performed the correlation analysis between KIRP immune checkpoint genes (CTLA4, HAVCR2, PDCD1, PDCD1LG2, and TIGIT) and high mutation frequency genes (TTN, MET, KMT2C, PKHD1, SETD2, and KMT2D)." (PMID 36618928, 2022). "In addition, we found that CD274 and PDCD1LG2 were correlated with gene markers in tumor-infiltrating immune cells." (PMID 33833994, 2021). "In our study, the risk alleles of PDCD1LG2 rs2381282, rs12237624, and rs78096119 were negatively associated with PD-L2 expression in non-tumor tissue, but not in tumor tissue." (PMID 34631591, 2021). "We have observed significant upregulation of PDCD1LG2 in tumor samples." (PMID 31796082, 2019). "The first and the best characterized strategy used in clinics is based on the inhibition of the interaction of programmed cell death 1 (PD1) present on the surface of T lymphocytes with its ligands PD-L1/CD274 and PD-L2/PDCD1LG2 expressed by tumor cells and antigen presenting cells." (PMID 31467175, 2019).
tumor (continued). "Of these, transmembrane glycoprotein NMB (Gpnmb), low affinity immunoglobulin gamma Fc region receptor II (Fcgr2), H-2 class I histocompatibility antigen, alpha chain, and programmed cell death 1 ligand 2 (Pdcd1lg2) are directly involved in tumor immune evasion." (PMID 29899869, 2018). "Intriguingly, classical M2 markers including Cd206 (Mrc1), Cd163, Pdl2 (Pdcd1lg2), Ccr3, Arg1 and many others were all markedly downregulated in TAMs isolated from the St2−/− background as compared with those isolated from tumours grown in wt mice." (PMID 27150562, 2016). "PDCD1LG2 may be a prognostic biomarker of HCC and may be associated with tumor immune escape." (PMID 38890507, 2024). "We evaluated the tumor immune landscape through the CIBERSORT algorithm, which indicated the upregulation of resting Myeloid Dendritic Cells (DCs), memory B cells, and naïve B cells and high expression of key immune checkpoint molecules (CD274 and PDCD1LG2) in the high-risk group." (PMID 38310291, 2024). "Also, critical immune checkpoint genes such as LAG3, PDCD1LG2, CD274, IDO1, PDCD1, and CTLA4 were evaluated because these genes are activated when T cells identify and attach to associated proteins on other cells, such as certain tumor cells." (PMID 37876438, 2023). "Furthermore, we discovered that L1CAM was linked to immune cell infiltration and ICG (CD274, LAG3, PDCD1LG2, CTLA4), and we hypothesized that L1CAM may have a regulatory role in the tumor microenvironment, influencing tumor growth and metastasis." (PMID 36212450, 2022). "Finally, the discovery that programmed cell death 1 ligand 2 (PD-L2) is upregulated on senescent tumor cells may open novel avenues to develop immunomodulatory senolytics in the near future." (PMID 33557090, 2021). "Interestingly, we found that ALDH3A2 co-expression might be negatively correlated with the PDCD1, PDCD1LG2, and CTLA4 genes, and positively associated with tumor purity." (PMID 33148208, 2020). "Our study revealed a correlation between MMP14 expression and various molecules regulating tumor immune cells, including CSF1R, HAVCR2, KDR, PDCD1LG2, TGFB1, CD70, CD86, and CXCL1." (PMID 40352589, 2025). "In group 0, several immune checkpoint and pro-inflammatory genes, including PDCD1LG2 (PD-L2), CD274 (PD-L1), HLA-A, CXCL10, and CD163, displayed relatively high expression, suggesting a more inflamed tumor microenvironment." (PMID 41517303, 2025). "This aligns with our broader analysis implicating chemokine ligands (CCL family), immune checkpoints (PD‐L1/CD274, PDCD1LG2, HAVCR2), and cell surface markers in shaping tumor immune phenotypes." (PMID 40693457, 2025). "Numerous transcripts related to immunological checkpoints, including SIGLEC15, PDCD1LG2 (PD-L2), TIGIT, PDCD1 (PD-1), CD274 (PD-L1), CTLA4, LAG3, and HAVCR2 (TIM3), are integral to tumor immune evasion mechanisms." (PMID 41194934, 2025). "Analyses of bulk RNA-seq of human ccRCC revealed that PDCD1LG2 and CD80 expression were upregulated in ccRCC tumours compared to normal kidney, as was expression of LGALS3, LGALS9, SELL and CD276." (PMID 40473819, 2025). "Several transcripts associated with immunological checkpoints, such as SIGLEC15, PDCD1LG2 (PD-L2), TIGIT, PDCD1 (PD-1), CD274 (PD-L1), CTLA4, LAG3, and HAVCR2 (TIM3), play a crucial role in tumor immune evasion." (PMID 40893939, 2025). "Further database analysis (TIMER2.0) showed that PDCD1 gene expression was positively correlated with the levels of immunosuppressive genes (CD274, PDCD1LG2, TGFB1, and IL10) in most human tumor types." (PMID 38441961, 2024). "IDO1 is positively correlated with CD274, TNFRSF9, TNFRSF4, PDCD1LG2, IDO2, and CD48 in many tumor types." (PMID 38539263, 2024).